ENSG00000239129
Synonyms: LOC124904117
Gene: Small nucleolar RNA gene on chromosome 17 (29,883,006 to 29,883,109, forward strand). Ensembl gene ENSG00000239129.
Gene Ontology:
Biological process: RNA processing
Cellular component: nucleolus
Homologues: Orthologues: rat LOC120101371 (70% identical). Paralogues in human: SNORD13E (82% identical), SNORD13 (81% identical), SNORD13P3 (81% identical), SNORD13D (80% identical), SNORD13P1 (76% identical).